PHPT1 (phosphohistidine phosphatase 1)
Description:
Exhibits phosphohistidine phosphatase activity.
Synonyms: PHP; PHP14; CGI-202; HSPC141; DKFZp564M173; bA216L13.10; HEL-S-132P
Tractability: Small molecule: it has a high-quality binding pocket. Antibody: its Gene Ontology location is reachable by antibodies, with high confidence; the Human Protein Atlas places it where antibodies can reach. PROTAC: ubiquitination databases record sites on it; its protein half-life has been measured; a small molecule that binds it is known.
Target class: Enzyme; Hydrolase
Gene: Protein-coding gene on chromosome 9 (136,848,724 to 136,851,039, forward strand). Ensembl gene ENSG00000054148.
Subcellular location: Cytoplasm
Subcellular location (Human Protein Atlas): Cytosol; Nuclear bodies; Nucleoplasm; Plasma membrane
Gene Ontology:
Molecular function: actin filament binding; calcium channel inhibitor activity; enzyme inhibitor activity; protein binding; protein histidine phosphatase activity; transmembrane transporter binding
Biological process: actin cytoskeleton organization; lamellipodium organization; negative regulation of T cell receptor signaling pathway; positive regulation of cell motility
Cellular component: cytosol; extracellular exosome; leading edge of lamellipodium; cytoplasm
Genetic constraint (gnomAD): Loss-of-function variants: 16 observed, 15.66 expected, observed/expected ratio (o/e) 1.02, 90% interval 0.69 to 1.55. The synonymous counts are far from expectation, so gnomAD's model fits this gene poorly and the ratio says little. Missense variants: 228 observed, 178.84 expected, observed/expected ratio (o/e) 1.27, 90% interval 1.14 to 1.42. Synonymous variants: 102 observed, 72.87 expected, observed/expected ratio (o/e) 1.4, 90% interval 1.19 to 1.65.
Homologues: Orthologues: chimpanzee PHPT1 (99% identical), macaque PHPT1 (98% identical), dog PHPT1 (86% identical), guinea pig PHPT1 (84% identical), mouse Phpt1 (83% identical), tropical clawed frog phpt1 (67% identical), zebrafish phpt1 (64% identical), Caenorhabditis elegans phip-1 (43% identical), Drosophila melanogaster janA (39% identical), Drosophila melanogaster CG18662 (30% identical), Drosophila melanogaster janB (29% identical), Drosophila melanogaster ocn (29% identical).
Diseases named in the same sentence as PHPT1 in open-access papers:
PHPT1 is named in the same sentence as 20 diseases in open-access papers, as found by Europe PMC text mining. Sharing a sentence is not in itself a finding about the gene and the disease. The quoted sentences say what the papers report.
lung carcinoma (8 papers, 2011 to 2024). "Among de-regulated proteins, PHPT1 protein plays a role in lung cancer cell migration/invasion and is revealed to be associated with cytoskeleton reorganization." (PMID 26955879, 2016). "PHPT1 has been found to be overexpressed in lung cancer and playing a role in cancer progression, migration and invasion." (PMID 28105922, 2016). "Mechanistically, in lung cancer, PHPT1 could activate the MAP kinase pathway, which in turn promotes cell proliferation and tumor growth." (PMID 39063217, 2024). "Furthermore, PHPT1 promotes cell migration and invasion in lung cancer." (PMID 39063217, 2024). "PHPT1 plays a role in the resistance to treatment in pancreatic cancer and in the resistance to erlotinib, an EGF receptor inhibitor used in lung cancer treatment." (PMID 39063217, 2024). "FBXO32 worked as an E3 ligase for PHPT1 ubiquitination, leading to reduction of PHPT1 accumulation, inactivation of the ERK/MAPK axis, which inhibited the proliferation of lung cancer cells." (PMID 35928868, 2022). "PHPT1 promotes proliferation in HCC and in EGFR mutant lung cancer cells." (PMID 39063217, 2024). "This includes the NME family of likely histidine kinases, as well as the protein histidine phosphatase LHPP which has multifaceted activity as a tumour suppressor for a range of cancers, and the histidine phosphatase PHPT1, which is an oncogene involved in lung cancer." (PMID 36048825, 2022). "Although it not known how PHPT1 regulates actin, targeted knockdown of PHPT1 expression resulted in the redistribution of actin from microspikes and filopodia to cortical microfilaments at the periphery of CL1-5 lung cancer cells." (PMID 23741372, 2013).
glioma (2 papers, 2009 to 2014). A benign or malignant brain and spinal cord tumor that arises from glial cells (astrocytes, oligodendrocytes, ependymal cells). "Additionally, in the PubMed UniGene ESTProfile database, glioma cells have high expression of PHPT1 mRNA, which correlates to the HPR finding for malignant glioma and glioblastoma cell lines, where the immunostaining was moderate to strong." (PMID 19396692, 2009).
pancreatic cancers (2 papers, 2022 to 2024). "High expression of PHPT1 RNA and protein levels appears to be positively correlated with poor prognosis in different cancers, such as HCC, lung and pancreatic cancers, and clear cell renal carcinoma." (PMID 39063217, 2024).
colorectal cancer (1 paper, 2016). A primary or metastatic malignant neoplasm that affects the colon or rectum. "Increase in expression of PHPT1, PPP2R5D, and two TRIB3 transcripts indicates that tumor-associated changes in alternative splicing can affect glucose metabolism in colorectal cancer." (PMID 28105922, 2016). "We first showed up-regulation of PHPT1 and PPP2R5D alternative transcripts in colorectal cancer." (PMID 28105922, 2016).
colorectal tumors (1 paper, 2016). "These eight isoforms encoded by OGDH, COL6A3, ICAM1, PHPT1, PPP2R5D, SLC29A1, and TRIB3 genes were up-regulated in colorectal tumors, and this is in concordance with the bioinformatics data." (PMID 28105922, 2016).
head and neck cancer (1 paper, 2018). A primary or metastatic malignant neoplasm affecting the head and neck. "Hence, PHPT1 and CDKN1A were significantly up-regulated at all time points in endometrial patients (respectively) while a significant up-regulation in head and neck cancer patients was observed for PHPT1 and CDKN1A only at 48 hr, after the 2nd RT fraction (respectively)." (PMID 29474504, 2018). "Overall, an up-regulation of PHPT1, CCNG1, CDKN1A, GADD45, and SESN1 was found in endometrial and head and neck cancer patients at all time points with the exception of SESN1." (PMID 29474504, 2018).
hyperinsulinemic hypoglycemia (1 paper, 2022). An inherited autosomal recessive syndrome characterized by the disorganized formation of new islets in the pancreas and congenital hyperinsulinism. "A recent study revealed that PHPT1 knockout mice developed hyperinsulinemic hypoglycemia in the neonatal period." (PMID 36278516, 2022).
leukaemia (1 paper, 2009). "In the HPR database, the relative PHPT1 protein expression level was moderate, 8%, in the only human leukaemia cell line analysed, but the presence or absence of duplication in this particular cell line is not known." (PMID 19396692, 2009).
T cell acute lymphoblastic leukaemia (1 paper, 2009). "Another example of PHPT1 being involved in a proliferation context is a recurrent 9q34 duplication in paediatric T cell acute lymphoblastic leukaemia that was found in 33% of the cases with increased mRNA expression of the PHPT1 gene." (PMID 19396692, 2009).
tuberculous pleurisy (1 paper, 2021). "A total of eight possible biomarkers of tuberculous pleurisy were screened (RPL17, UBA7, NDUFB8, UQCRFS1, JUNB, PSMC4, PHPT1, and MAPK11)." (PMID 34925441, 2021).
tumor (7 papers, 2014 to 2025). "All of these studies suggest that PHPT1 acts as a promoter of tumor progression." (PMID 39063217, 2024). "However, the exact role of PHPT1 as a histidine phosphatase in tumor progression remains to be elucidated." (PMID 39063217, 2024). "Rather, most of the studies seem to show that PHPT1 is involved in tumor progression." (PMID 39063217, 2024).
cancer (4 papers, 2009 to 2022). A tumor composed of atypical neoplastic, often pleomorphic cells that invade other tissues. "At the same time, in the HPR project, the PHPT1 expression in human tissues, cancers, and cell lines has been investigated." (PMID 19396692, 2009).
PHPT1 also shares sentences with these, for which no sentence is quoted: cervical cancer (2 papers); hepatocellular carcinoma (2); bladder cancer (1); colon tumors (1); glioblastoma (1); liver cancer (1); malignant glioma (1); Obesity (1).